WASHC4 (WASH complex subunit 4)
Description:
Acts as a component of the WASH core complex that functions as a nucleation-promoting factor (NPF) at the surface of endosomes, where it recruits and activates the Arp2/3 complex to induce actin polymerization, playing a key role in the fission of tubules that serve as transport intermediates during endosome sorting.
Synonyms: SWIP; KIAA1033; MRT43
Tractability: PROTAC: ubiquitination databases record sites on it.
Gene: Protein-coding gene on chromosome 12 (105,107,324 to 105,169,134, forward strand). Ensembl gene ENSG00000136051.
Subcellular location: Early endosome
Subcellular location (Human Protein Atlas): Nucleoplasm
Gene Ontology:
Molecular function: protein binding
Biological process: endosomal transport; endosome organization; nuclear envelope budding; regulation of Arp2/3 complex-mediated actin nucleation
Cellular component: BLOC-1 complex; early endosome; endosome; nucleoplasm; WASH complex; early endosome membrane
Genetic constraint (gnomAD): Loss-of-function variants: 33 observed, 68.86 expected, observed/expected ratio (o/e) 0.48, 90% interval 0.36 to 0.64. The upper end of that interval is the gene's LOEUF score, 0.64, which puts it in group 2 of 6, group 1 being the genes least tolerant of losing a copy. Missense variants: 642 observed, 691.17 expected, observed/expected ratio (o/e) 0.93, 90% interval 0.87 to 0.99. Synonymous variants: 238 observed, 235.73 expected, observed/expected ratio (o/e) 1.01, 90% interval 0.91 to 1.12.
Homologues: Orthologues: chimpanzee WASHC4 (99% identical), macaque WASHC4 (99% identical), dog WASHC4 (98% identical), pig WASHC4 (98% identical), mouse Washc4 (97% identical), guinea pig WASHC4 (95% identical), rat Washc4 (94% identical), rabbit WASHC4 (90% identical), tropical clawed frog washc4 (88% identical), zebrafish washc4 (85% identical), Drosophila melanogaster SWIP (27% identical), Caenorhabditis elegans Y53F4B.21 (21% identical).
Diseases named in the same sentence as WASHC4 in open-access papers:
WASHC4 is named in the same sentence as 8 diseases in open-access papers, as found by Europe PMC text mining. Sharing a sentence is not in itself a finding about the gene and the disease. The quoted sentences say what the papers report.
Intellectual disability (2 papers, 2017 to 2021). "In particular, an autosomal recessive mutation in WASHC4 (c.3056C>G; p.Pro1019Arg) was identified in a cohort of children with non-syndromic intellectual disability." (PMID 33749590, 2021).
cancer (2 papers, 2022 to 2024). A tumor composed of atypical neoplastic, often pleomorphic cells that invade other tissues. "WASH complex subunit 4 (Washc4) one of the top hits detected in KO EVs is involved in endosomal sorting and actin cytoskeleton remodeling and other factors contributing to EVs biogenesis, cargo sorting, as well as cancer-related proteins were differently expressed." (PMID 38942797, 2024).
WASHC4 also shares sentences with these, for which no sentence is quoted: autosomal recessive intellectual disability (1 paper); Dyskinesia (1); hereditary spastic paraplegia (1); penile carcinoma (1); penile squamous cell carcinoma (1); tumour (1).